MIR8076 (microRNA 8076)
Synonyms: hsa-mir-8076
Gene: MicroRNA gene on chromosome 3 (113,432,118 to 113,432,200, reverse strand). Ensembl gene ENSG00000275670.
Homologues: Orthologues: chimpanzee MIR8076 (100% identical).